INS (insulin)
Diseases named in the same sentence as INS in open-access papers (continued):
Sharing a sentence is not in itself a finding about the gene and the disease.
diabetes (continued). "Chronic low fluidity in our membranes has several diabetes-promoting consequences, including impairing insulin secretion and signaling, reduced efficacy of GLUT4 localization to membranes and hardening of blood vessels." (PMID 27671740, 2016). "In diabetes mellitus type 2 subjects, 10 days of cold acclimation increased peripheral insulin sensitivity by 43%." (PMID 27528872, 2016). "The MDKT, including the general diabetes subscale and the insulin-use subscale, is perceived as a relevant and appropriate instrument for measuring diabetes knowledge among nursing personnel in nursing home and home-based care." (PMID 27366112, 2016). "Among the peripheral activities, recent studies demonstrate a novel ability of GHRH analogs to increase and preserve insulin secretion by beta-cells in isolated pancreatic islets, which makes them potentially useful for diabetes treatment." (PMID 27777568, 2016). "Einleitung: Diabetes Mellitus beschreibt die Dysregulation des Glukosemetabolismus auf Grund von pathologischer Insulin-Sekretion, reduzierter Insulin-Effizienz oder beidem." (PMID 26955508, 2016). "The aim of this study was to compare the efficacy, safety, costs, and cost-effectiveness of biphasic insulin aspart 30 (BIAsp 30) with NPH plus regular human insulin (NPH/Reg) in patients with type 2 diabetes mellitus (T2DM)." (PMID 27278922, 2016). "Medication use of participants with diabetes included statins, metformin, sulfonylureas or insulin, while some were underwent dietary therapy alone." (PMID 26938557, 2016). "For females, low BMI in early diabetes, intensive insulin therapy, and higher insulin dose, additionally to longer disease duration and age were associated with greater increases in BMI." (PMID 27429649, 2016). "Microarrays revealed an altered miR signature in the skeletal muscle of insulin resistant rats, patients with pre-diabetes and patients with T2DM." (PMID 27163678, 2016). "The combination of insulin sensitivity and hypoglycemic unawareness, characteristic of this condition, is known as “brittle” diabetes." (PMID 27605208, 2016). "Expression of nuclear human SREBP-2 in beta cells resulted in severe diabetes due to defects in glucose- and potassium-stimulated insulin secretion." (PMID 26973702, 2016). "Glycated albumin regulates VEGF expression to promote proteinuria and glomerulosclerosis in diabetes, suppresses insulin secretion in pancreatic β-cells, and stimulates cultured retinal microglia to secrete inflammatory cytokines." (PMID 27034961, 2016). "The data show that humoral and cellular anti-insulin immune responses are detectable in dogs with diabetes." (PMID 27031512, 2016). "In the United Kingdom Prospective Diabetes Study (UKPDS), metformin reduced the risk of MI more than sulfonylureas (SUs) or insulin in a small cohort of obese patients with T2DM." (PMID 27417914, 2016). "For the general diabetes scale, removing item 6 also reduced the Akaike information criterion from 1694.0 to 1640.0, and removing item 19 from the insulin-use subscale improved the Akaike information criterion from 821.6 to 800.1." (PMID 27366112, 2016). "The existence of atrophic islets and reduced and dispersed beta cells indicated that the source of diabetes was the reduced plasma insulin due to islet atrophy, as well as the reduced islet insulin content and secretion." (PMID 26459400, 2016). "The reprogrammed cells efficiently processed proinsulin to insulin, contained insulin storage granules, secreted insulin in response to glucose, and rescued diabetes in a streptozotocin mouse model." (PMID 27243814, 2016). "Diabetes mellitus (DM) is a group of metabolic disorders resulting from defects in insulin secretion and/or action that manifests itself with hyperglycemia leading to the dysfunction and damage of various organs, including the salivary glands." (PMID 27893660, 2016).
diabetes (continued). "Insulin resistance is described as the inability of insulin to regulate blood glucose level and usually leads to hyperglycemia accompanied by metabolic syndrome development including obesity and diabetes." (PMID 27547453, 2016). "Hypoglycemia, which occurs commonly during and following exercise in people with diabetes, is thought to be due to attenuated counterregulation in the setting of therapeutic insulin excess." (PMID 27597762, 2016). "Out of the remaining 12 diabetes patients on insulin, three got their insulin therapy cancelled and another eight had their insulin doses reduced by 27.6±16.4% on average." (PMID 27664051, 2016). "The ability to maintain a true and complete diabetes diary that enables users to record a range of factors in daily management is important to adults with T1DM who are actively engaged in their insulin self-management." (PMID 27629774, 2016). "From this study, it is concluded that combination of insulin, pioglitazone and synbiotic is useful in treating diabetes." (PMID 27051195, 2016). "Their domains usually capture behavioral characteristics related to diabetes management, such as insulin administration, meal plans, frequency/intensity of exercises, frequency of blood glucose monitoring, and hypoglycemia." (PMID 27478510, 2016). "Pathways leading from obesity to diabetes have also been identified, including the development of insulin resistance through the disruption of insulin signaling pathways due to lipolysis, the release of adipokines and inflammation." (PMID 27701452, 2016). "Touch screen technology and user-friendliness have been incorporated in Tandem diabetes Care’s T-Slim insulin pump." (PMID 26742082, 2016). "Three concepts regarding insulin therapy for diabetes, such as Lantus (ie, insulin glargine injection), Humalog (ie, insulin lispro injection), and Actos (ie, pioglitazone hydrochloride) in blog postings and questions/answers appeared with high frequency." (PMID 27884812, 2016). "Type 2 diabetes mellitus has two major features: desensitization of peripheral target tissues/organs to the actions of insulin, i.e., insulin resistance, and insufficient response of β-cell to glucose stimuli." (PMID 27070590, 2016). "Of the 648 individuals classified as having diabetes in the household enumerations, only one was consistent with type 1 diabetes based on an age at diagnosis under the age of 20, continuous insulin use since diagnosis and normal weight." (PMID 27266869, 2016). "Vascular dysfunction is an early event in the development of diabetes, and defective insulin signaling in the vasculature has been reported to be sufficient and necessary for the development of systemic insulin resistance." (PMID 27128347, 2016). "For a long time, central nervous system (CNS), being an insulin independent organ, was thought to be spared from complications of diabetes mellitus (DM)." (PMID 26925421, 2016). "Consistent with this view, insulin replacement therapy was shown in animal models of T1D to reverse the deleterious effects of diabetes on the skeletal system." (PMID 27159053, 2016). "Currently, diabetes therapy is based on the use of hypoglycemic agents (sulfonylureas, biguanides, and insulin), on lifestyle changes, exercise, and requires lifelong treatment." (PMID 27057112, 2016). "Transplanted cPB cells exhibit glucose-stimulated insulin secretion in vivo and protect mice from chemically induced diabetes." (PMID 26733021, 2016). "Defect in insulin activity required for T-lymphocytes in diabetes leads to abnormal T-lymphocyte proliferation and enhanced ADA activity." (PMID 28050278, 2016). "Insulin was noted as the medication for chronic disease in 54.8 % of patients with diabetes mellitus, and metformin was used in 47.3 % of the patients with diabetes mellitus." (PMID 27495247, 2016).
diabetes (continued). "Most patients considered the assistance of the peer educator essential, including diabetes management tasks, such as monitoring of glycaemia and self-injection of insulin." (PMID 26798483, 2016). "The medical condition category included variables related to heart attack, angina, cancer, snoring, depression, asthma, diabetes, and insulin use." (PMID 26835413, 2016). "Maternal obesity potentiates the deleterious effects of insulin-insufficient diabetes on offspring kidney health, particularly renal inflammation and oxidative stress." (PMID 27277011, 2016). "Adult mice were subjected to streptozotocin (STZ) diabetes and infused with exendin-4/insulin/saline from 0 to 4 or 4–12 weeks." (PMID 26597728, 2016). "Diabetes mellitus is a group of metabolic diseases characterized by hyperglycemia resulting from defects in insulin secretion and/or insulin action." (PMID 27455312, 2016). "As pharmaceuticals, sulfonylurea derivatives help control diabetes by increasing insulin secretion from β cells, which results in a lowering of blood glucose." (PMID 26978842, 2016). "Insulin, which was introduced almost a century ago, dramatically changed the treatment for diabetes, and still plays an important role in disease management." (PMID 26635356, 2016). "Apart from higher mean levels of haemoglobin A1c in patients before use of insulin or the group of other diabetes drugs, and higher levels of creatinine among those prescribed sulphonylureas or insulin, the mean values were similar across the six groups." (PMID 27413012, 2016). "The extent of amyloid deposition correlates with the clinical severity of diabetes, with the impairment in insulin secretion and glucose metabolism, and with the severity of beta-cell loss." (PMID 26961231, 2016). "Glycemic control is the mainstay of treatment in patients with diabetes mellitus and can be achieved via medical nutritional therapy, physical activity, oral medications, and insulin therapy." (PMID 27278922, 2016). "In this study, we investigate how measures of insulin secretion and other clinical information affect long-term glycemic control in patients with type 2 diabetes mellitus." (PMID 26849676, 2016). "In future study, we can prove it by observing the changes of miR-155 expression in different insulin-sensitive tissues and blood during the development of diet-induced obesity and diabetes in mice." (PMID 27711113, 2016). "As for the treatment of diabetes, at last follow-up 38.3% of the patients were treated with insulin, 15% with oral diabetes medications." (PMID 27814399, 2016). "PPARγ-deficient neonatal mice were rescued from embryonic lethality by epiblast-restricted recombination and showed marked lipodystrophy with diabetes but inappropriately “normal” levels of serum insulin." (PMID 27505464, 2016). "Function and survival of pancreatic β-cells, as well as the responsiveness of insulin-sensitive tissues to insulin, play an important role in diabetes mellitus, and both are regulated by the SphK/S1P axis." (PMID 27445808, 2016). "Beta cell killing starts long before diabetes onset, but interestingly the increase in beta cell death is subtle and sporadic prior to diagnosis, with only a mild repercussion on insulin secretion." (PMID 26918165, 2016). "In both pre-diabetes and diabetes subjects, insulin (30 min), C peptide (30 min), HOMA-β, DI30, DI120, and (ΔIns30/ΔGlu30)/HOMA-IR were significantly lower than those in the normal glycemic subjects." (PMID 27267043, 2016). "This patient was diagnosed in her teens in the early 1990s, when all slim adolescent patients with diabetes would have been assumed to have type 1 diabetes and automatically treated with insulin." (PMID 27330718, 2016). "It is known that reduced insulin sensitivity is present long before the onset of diabetes and the characteristic pathophysiologic disturbance is responsible for the development of type 2 diabetes." (PMID 27274905, 2016).
diabetes (continued). "Oral administration of insulin using intestinal mucoadhesive devices avoids the need for routine insulin injections for the management of diabetes." (PMID 29313019, 2016). "This was also reflected by a greater increase in student confidence in managing patients on both IV and s/c insulin than in other areas such as diagnosing diabetes and diagnosing and managing hypoglycaemia and diabetic ketoacidosis." (PMID 26956764, 2016). "Here, the authors show TSC22D4 inhibition improves insulin sensitivity in several mouse models of diabetes, which they attribute at least in part to the induction of secreted LCN13." (PMID 27827363, 2016). "It is reported that there is a relationship between TNF-α increase in diabetes and impairment of insulin signaling pathway by increasing serine phosphorylation of IRS-1 which inhibits IR tyrosine kinase activity and leads to downstream signaling." (PMID 27579151, 2016). "Systematic reviews done on the patient preferences for non-insulin diabetes medications during 2007–201231,32 have shown the importance of incorporating patient preferences into treatment decisions." (PMID 27429746, 2016). "Liver-specific p85α knockout also increased insulin sensitivity, while p85α haploinsufficiency protected mice with concomitant heterozygous knockout of the insulin receptor and Irs1 from overt diabetes." (PMID 27766312, 2016). "More specifically, E4orf1 provides a template to enhance glucose disposal by bypassing the impaired proximal insulin signaling, which is common in diabetes and obesity." (PMID 27537838, 2016). "Hyper-glycemia, low plasma insulin, atrophic pancreatic islets, reduced beta cell mass and depletion of islet insulin content are clear signs of STZ diabetes." (PMID 26459400, 2016). "Diabetes mellitus is a metabolic disease characterized by hyperglycemia due to defects in insulin secretion or its action." (PMID 26984821, 2016). "Modern flexible multiple daily injection (MDI) therapy requires people with diabetes to manage complex mathematical calculations to determine insulin doses on a day to day basis." (PMID 27629774, 2016). "Later, the 1977 UKPDS trial randomized patients to either standard or intensive diabetes care with either insulin, sulphonylurea or metformin." (PMID 27716274, 2016). "Vaccine-induced Treg cells thus efficiently suppressed diabetes induction by an ongoing insulin-reactive CD8+ T cell response." (PMID 27406624, 2016). "Sham-treated Akita mice developed full-blown diabetes when random glucose was measured on day 31, whereas long-acting half- dose insulin clearly prevented onset of hyperglycemia." (PMID 28702245, 2016). "The serum insulin level significantly decreased as a result of diabetes in the D group, which was restored during a 6-week of oral administration of RJ in the D/R group (P=0.000)." (PMID 27602318, 2016). "For example, lowering insulin/IGF-1 signaling in worms and flies extends lifespan but can cause diabetes and cardiovascular disease in human." (PMID 26934328, 2016). "Treating gestational diabetics through diet modification, exercise, and drugs (e.g., insulin and oral anti-diabetic agents, including metformin) improves maternal, fetal/neonatal, and offspring outcomes." (PMID 27555877, 2016). "Exercise training (ExT) reduces blood glucose, body fat, and insulin resistance and improves glycemic control, lipid metabolism, and baroreflex sensitivity in diabetes." (PMID 26989452, 2016). "Diabetes mellitus is a group of metabolic diseases characterised by chronic hyperglycaemia resulting from defects in insulin secretion, insulin action, or both." (PMID 26758371, 2016). "Because management of diabetes requires frequent injections of insulin, particular attention has been paid to making the delivery of insulin easier, safer, and less painful, which well fit the properties of delivery via microneedles." (PMID 28773770, 2016).
diabetes (continued). "In type 2 diabetes mellitus the prevalence is less, but incidence similarly rises with length of duration of insulin or sulphonylurea therapy." (PMID 26893294, 2016). "Blood glucose, plasma insulin, C-peptide I, C-peptide II, and glucagon were measured at various times during development of diabetes in Akita mice." (PMID 28702245, 2016). "The most common type, the type 2 diabetes mellitus (DM 2), makes up 90–95 % of the cases and is characterized by impaired action and/or insulin secretion." (PMID 26889209, 2016). "In animal trials, the intake of magnesium supplements prevented a drop in resistance to insulin or glucose intolerance and postponed the development of spontaneous diabetes mellitus." (PMID 26999166, 2016). "Our study is the first to show that the initial dose of insulin is related to the ratio of RBG/RI in Chinese new onset patients with diabetes who use the insulin pump therapy." (PMID 26697503, 2016). "T2DM, which is characterized by insulin resistance and high insulin levels, accounts for 90–95% diabetes mellitus." (PMID 26901856, 2016). "The item-total correlations were >0.2 for items 3, 5, 6 and 10–14 in the general diabetes subscale and >0.2 for items 20–22 in the insulin-use subscale." (PMID 27366112, 2016). "Studies suggest that people with reduced insulin sensitivity or prediabetes can prevent or delay the onset for diabetes, and in some cases even return their insulin sensitivity to normal, by lifestyle modifications such as weight loss and physical activity." (PMID 27274905, 2016). "Nevertheless, additional strategies to enhance insulin levels and signaling are of great interest in the treatment of diabetes and metabolic disease." (PMID 27478532, 2016). "Among these studies, two compare insulin with agents that have been withdrawn from the market, (tolbutamide, a sulfonylurea and phenformin, in the University Group Diabetes Program study)." (PMID 27391319, 2016). "Eight weeks of treatment with SER140 reduced the incidence of diabetes by more than 50% compared with vehicle, decreased blood glucose, and increased plasma insulin." (PMID 26953152, 2016). "Insulin insensitivity, or decreases in insulin receptor signalling, leads to diabetes mellitus type 2." (PMID 26901760, 2016). "Additionally, HOMA-β values remained low in subjects who had higher concentrations of total PCBs at the 2-year follow-up, suggesting that higher levels of certain POPs in children might be responsible for impaired insulin secretion, which potentially increases the risk of diabetes later in life." (PMID 27266903, 2016). "This is the first study to investigate endogenous insulin secretion in longstanding diabetes using islet autoantibody data at time of diagnosis." (PMID 27591853, 2016). "Among the included patients, 165 had diabetes; 123 of these diabetic patients were on oral hypoglycemic agents and 114 were using insulin." (PMID 28000723, 2016). "In the next experiment, we tested if parameters altered by alloxan-induced diabetes can be reversed by insulin therapy." (PMID 27432282, 2016). "Diabetes, a group of metabolic disease, is characterized by chronic hyperglycemia due to defects in insulin secretion and/or insulin action." (PMID 26819084, 2016). "In contrast, previous reports included both diabetic and non-diabetic subjects, with the former being the minority (<11 %), or they excluded patients taking insulin-sensitizing medication or those with diabetes." (PMID 27491472, 2016). "Concerning type 2 diabetes mellitus, zinc is an important component for insulin synthesis that functions by stabilizing insulin hexamers and their pancreatic storage." (PMID 27343205, 2016). "In this study, we aimed to establish a fusion protocol of bone marrow−derived human MSCs with the rat beta-cell line (INS-1E) as well as human isolated pancreatic islets in order to generate insulin producing beta-MSCs as a cell-based treatment for diabetes." (PMID 27374092, 2016).